IL5 (interleukin 5)
Diseases named in the same sentence as IL5 in open-access papers (continued):
Sharing a sentence is not in itself a finding about the gene and the disease.
infection (continued). "We observed that infected WT mice exhibit a mixed response of Th1 and Th2 already in the initial stage of infection (3dpi), represented by an increase in IFN- γ, IL-1β, IL-33, IL-13 and IL-5." (PMID 34324507, 2021). "The top predicted transcriptional regulators (P < .01) at 2 h post-infection were wortmannin, CSF3 which is predicted to be activated, LEP, JNK, and, IL5 which are predicted to be inhibited." (PMID 33382951, 2021). "The PLS showed that the levels of GMCSF, Fractalkine, IFNg, ITAC, IL-1ß, IL-2, IL-5, IL-7, IL-8, IL-10, IL-12, IL-17α, IL-21, IL-23, MIP-1ß, and TNFα had higher impact on the separation between the uninfected and the pre-infection cohort." (PMID 33731158, 2021). "Levels of G-CSF, IL-1β, IL-5, and IL-6, and chemoattractant VEGF were significantly altered during the acute phase of infection with concomitant detection of bacterial loads in the blood." (PMID 34451491, 2021). "Compared to sham treatment, RV-C15 infection significantly increased mRNA expression of IFN-γ, CXCL10, CXCL1, CXCL2, TNF-α, IL-12, IL-25, IL-13 and IL-5." (PMID 33968043, 2021). "Retrospective analysis of human samples after an Italian CHIKV outbreak revealed an increase in IL-6 during the acute phase of infection, and low levels of IL-1β, TNF-α, IL-12, IL-10, IFN-γ, and IL-5 that increased as disease progressed to the chronic state." (PMID 34106915, 2021). "The percentages of IL-4+, IL-5+, IL-6+, IL-21+, IL-1α+, and IL-17+ γδT cells were increased (p < 0.05), but the percentage of IFN-γ-expressing γδT cells decreased (p < 0.05) post-infection." (PMID 33588839, 2021). "For instance, serum and plasma from patients with a mild to moderate infection contained significantly greater levels of MCP-3, IL-1α, TNFβ, IL-4, IL-5, IL-6, IL-8, IL-9, and IL-13 compared to serum and plasma from patients that were critically ill." (PMID 34790978, 2021). "This IL-5 is mainly produced by a small number of ILC2s in the IAV-infected lung, beginning 5–7 days post-infection, which also corresponds to induction of IAV-specific lung adaptive immunity." (PMID 34960631, 2021). "Of the previous general inflammatory markers, we looked specifically at IL-5 and KC/GRO concentration during active infection." (PMID 34475490, 2021). "In contrast, IL-4, IL-5, IL-6, and epidermal growth factor (EGF) reached peak levels late during infection, between 15 and 25 DPI, before dropping considerably at the terminal time point." (PMID 33436428, 2021). "Concentrations of two cytokines, IL-5 and IL-8, decreased in either infected rhesus macaques compared to the control or NHP-2 (uninfected) throughout the infection." (PMID 34451491, 2021). "Among serum molecules identified in non-neurological and neurological diseases in the acute phase of the infection, 12 (IL-1β, IL-6, TNF, IL-2, IL-7, IL-17A, IL-15, IFN-α, IL-5, IL-13, IL10, and GM-CSF) were shared by both networks." (PMID 33776990, 2021). "Our data indicate that HDM-sensitized mice exhibit elevated IL-4 and IL-5 levels at various time points throughout pH1N1 infection, and conversely, lower IFN-γ on day 6 post-infection." (PMID 33653328, 2021). "Similar reductions in AHR and levels of IL-5 and IL-13 in the BALF were seen after re-infection when anti-TSLP was administered prior to the primary infection of neonatal mice compared to mice administered a control antibody." (PMID 32397226, 2020). "After infection, the proinflammatory cytokines IFN-γ and IL-5 were reduced by the administration of 25(OH)D3." (PMID 32635656, 2020). "Anti-HMGB1 therapy significantly reduced the concentrations of IL-4, IL-5, and IL-13 in the BALF at day 21 post-infection compared to a group that was infected and treated with control antibodies." (PMID 32397226, 2020).
infection (continued). "In unpretreated MSC group, a comparable level of IFN-γ and IL-5 compared to infection control was observed, and in the TLR2+IFN-γ-treated MSC group, only a medium increase of the level of IFN-γ and comparable IL-5 level to the infection control were visible." (PMID 32503644, 2020). "The high IL-5 levels seen in STAT1 KO and STAT1/RAG DKO mice may contribute to early weight loss and more severe thickening of the basement membrane of bronchial epithelial cells, which was exaggerated in STAT1/RAG1 DKO mice compared with STAT1 KO mice following infection." (PMID 32310998, 2020). "However, it seems unlikely that IL-5 has an instrumental role in the lethality of LCMV-infected STAT1 KO mice since STAT1/RAG1 DKO mice had greater IL-5 levels than STAT1 KO mice following infection, suggesting that adaptive immune cells inhibit the production of IL-5." (PMID 32310998, 2020). "The protein levels of IL-5, IL-6, IFNγ, G-CSF, and MCP-1 (CXCL2) were significantly higher in ZBP1−/− mice compared to the WT mice at day 4 after infection." (PMID 31572318, 2019). "A general upregulation of the immune response was found when comparing dual with single infection, specifically, of the significant variables 71% were upregulated such as IL4, IL5, IFNγ, and IL10." (PMID 31871660, 2019). "Among the cytokines analyzed for this study, IL-4, IL-5, IL-10, IL-13, and TGF-b participate in the resolution of infection-related pulmonary inflammation." (PMID 31271354, 2019). "On the other hand, M2 macrophage-related genes (PPARγ, TGF-β, STAT3, IL5 and STAT6) were significantly up regulated after 24 h of infection." (PMID 30918280, 2019). "Airway epithelial damage by allergen and/or infection leads to the production of TSLP, IL-25 and IL-33, which in turn stimulate ILC2 cells to produce large quantities of IL-5 and IL-13." (PMID 31415658, 2019). "Immunodeficient mice (IL-4R−/−, IL-5−/−, IL-4R−/−/IL-5−/−, dblGATA BALB/c mice) exhibited increased numbers of peripheral MF throughout the infection compared to WT controls." (PMID 31109364, 2019). "Other cytokines that were slightly elevated at day 2 of infection were Th17-dependent IL-17A, Th1-dependent gamma interferon (IFN-γ), and IL-5." (PMID 31548315, 2019). "Our analysis of naturally infected calves shows an association with increased eosinophil counts, IL-4 production, and IL-5 transcription and decreased IFN-γ production, indicating polarization toward a type 2 response as infection progresses." (PMID 28993458, 2018). "Some interactions between peripheral infection and parity were noted for TNF (p = 0.054), IL-12 (p = 0.061), IL-2 (p = 0.003), IFN-γ (p = 0.025), IL-8 (p = 0.151), and IL-5 (p = 0.031)." (PMID 29743113, 2018). "Not only the percentages of MHC II-, CD69-, and NKG2A/C/E-expressing cells but also the percentages of IL-4-, IL-5-, and IL-17-producing cells in TLR3+ NK cells increased significantly after infection (P < 0.05)." (PMID 30246036, 2018). "The IL‐4 and IL‐5 expression levels from the NP30‐immunized mice were higher than those from the control group, and IL‐4 levels were also higher in the 4‐week post‐infection group." (PMID 29577333, 2018). "The results showed that compared to others the changes of TNF-, Il-12, IL-5, and GM-CFS were significant, and the level of these cytokines in serum increased on week 5 after infection, peaked on week 6, and then began to decrease." (PMID 28539607, 2017). "Circulatory IFN-γ, IL-4, IL-5, IL-6 and TNF-α were increased in WT mice after infection with PcAS (respectively, p = 0.004, 0.004, 0.0081, 0.004 and 0.004)." (PMID 29062028, 2017). "Similar to infection during or after HDM sensitization, infection prior to allergen exposure triggered airway infiltrations of CD4+ T cells secreting increased amounts of IL-17, IFN-γ, and IL-5." (PMID 29184554, 2017).
infection (continued). "To ascertain this FACS data, we determined the relative expression of Th2 and Treg related cytokines (IL-4, IL-5, IL-10 and TGF-β) in the liver of non-infection and C. sinensis infection mice by the quantitative RT-PCR." (PMID 28151995, 2017). "Production of Th2 cytokines (IL-4, IL-5, IL-10 and IL-13) by MLN cells similarly peaked at day 6–7 post infection and gradually declined thereafter." (PMID 28651009, 2017). "In contrast, in Cftr−/−mice, both types of ILC2 steadily increased throughout the infection along with the expression of the ILC2 transcription factors, Rora, and Gata3 and the production of ILC2 effector cytokines, IL-5 and IL-13." (PMID 28090087, 2017). "Processes related to cytoskeletal remodeling and cellular junctions, as well as inflammatory responses (IL-2, IL-5, IL-18, CCL2, TNF, IFN, and TGF-β signaling) were also upregulated following infection with C. concisus BAA-1457." (PMID 27677841, 2016). "However, some general points can be made: Th2-associated cytokine levels were higher overall, as might be expected given the nature of the infection; IL-3, IL-4, IL-5, IL-10 and IL-13, were all elevated in popLN cells from infected limbs, particularly so when re-stimulated with Brugia antigen." (PMID 27992545, 2016). "Therefore, it appears that eosinophil survival is promoted by extrinsic (LPS) and intrinsic (IL-33) danger signals particularly under conditions of low IL-5 concentrations as it may occur in certain anatomical sites where eosinophils get recruited during infection or tissue injury." (PMID 27690378, 2016). "There was a significant increase at day 7 relative to day 5 post-infection in abundance of interleukins (IL) including IL1B, IL2, IL4, IL5, IL6, IL10 and IL13." (PMID 27311020, 2016). "Rapid and more-sustained elevations in IL-1ra, MIP-1α, IL-5, IL-10 and IL-17 levels were followed by IL-1β, IL-2, IL-7, IL-9, IL-12, IL-15, IFN-α2, MIP-1β, FGF-2 and GM-CSF at over 2 months post-infection, and accompanied by the recovery of CD4+ cells." (PMID 27830756, 2016). "In vivo, infection of Kdm5bfl/fl-CD11c-Cre+ mice with RSV resulted in higher production of IFN-γ and reduced IL-4 and IL-5 compared to littermate controls, with significantly decreased inflammation, IL-13, and mucus production in the lungs." (PMID 26083387, 2015). "Whereas, hydatid crude antigen induced expression of IL-4, IL-5, IL-6 and IFN-γ in PBMCs isolated from patients and showed correlation with the infection status." (PMID 26578348, 2015). "Similarly, basophils are known to act as effectors to promote parasite killing during challenge infections of immunized animals, perhaps through antibody dependent mechanisms, while neutrophils have been demonstrated to attack helminth larvae in response to IL-4 and IL-5." (PMID 24498448, 2014). "Levels of IL-4, IL-5, IL-8, IL-12/23p40, IL-17, G-CSF, GM-CSF, sCD40, and RANTES were either unchanged in post-infection samples or below levels of detection." (PMID 25412185, 2014). "Mice lacking CC16 demonstrated significantly higher concentrations of Th2 cytokines IL-5 and IL-13 in BALF for several days following the infection." (PMID 24735334, 2014). "In a control experiment, mice were immunized with Ad.IL5, Ad.IL6 or Ad.IL23 alone to exclude any direct effects of the cytokine vectors on subsequent FV challenge infection." (PMID 24349306, 2013). "We found similar results with primary T cell lines from deer mice at 10 days post infection with SNV, in which Ifng, Il4, Il5, Il10 and Tgfb were elevated." (PMID 23570545, 2013). "The same variables as those modeled for the IL-5 boost: i.e. sex, village-group and age-group, pre-treatment infection intensities, SWA-IgE levels and 24-hr post-treatment eotaxin, were entered, along with IL-5 levels 24-hr post-treatment." (PMID 23556029, 2013).
infection (continued). "After larvae activate complement, vasoactive and chemotactic peptides (C3a and C5a) are generated, and these peptides mobilize eosinophils to the area of infection independently of specific mechanisms (CD4+ and IL-5)." (PMID 23509684, 2013). "IL-5 levels were boosted 24-hr post-treatment and found to be dependent on pre-treatment SWA-IgE levels, eosinophil count and infection intensity." (PMID 23556029, 2013). "The cellular responses to a culture filtrate protein of Mtb however is generally a slowly evolving one and gradually builds up (IL-2, IL-5, IFN-γ and TNF-α) over the course of infection with M. ulcerans (right column)." (PMID 23516649, 2013). "Contrary to the pattern of Th1-type response gene expression, 5 of the 14 Th2 type response genes (IL5, CCL11, CCR3, IL1RA and GATA3) were significantly downregulated at 2, 4, 8 and 12 weeks post-infection." (PMID 23448601, 2013). "A multiplexed bead assay was used to measure plasma levels of IL-5, IL-10, IL-12, IL-13, IFN-γ and TNF in BALB/c mice immunized against P. berghei K173 by repeated infection and drug cure before the first pregnancy." (PMID 24180253, 2013). "For Ad.IL5 and Ad.IL23, this improvement correlated with enhanced neutralizing antibody titers after FV challenge infection, whereas mice co-immunized with Ad.IL6 showed improved virus-specific CD4+ T cells." (PMID 24349306, 2013). "Th2-mediated differentiation of progenitor eosinophils (i.e. resident eosinophils), modulated by IL5 and IL13, also played an important role in helminth reduction in single infection, as indicated by the perturbation results." (PMID 22253585, 2012). "The only cytokine influenced by the 13 bp deletion in smeZ was IL-5; IL-5 was higher in GAS-M3smeZ-M89 infection, not only at the site of infection but also in the serum." (PMID 23049698, 2012). "The other strains kept the infection for 50 days (IL-5-/- KO), 40 days (IFN-γ-/-/IL-5-/- DKO), 20 days (IFN-γ-/- KO) and 5 days (IL-4R-/- KO)." (PMID 22348321, 2012). "In IFN-γ-/-/IL-5-/- DKO larvae recovered 40 days post infection were all from the subcutaneous tissues whereas in IFN-γ-/- KO mice, larvae recovered 20 days post infection were from the subcutaneous tissues, muscles and genital organs." (PMID 22348321, 2012). "In contrast, significant levels of IL-5 were detected in the supernatant of cells from group 5, 6 and 7, in response to rCPs SLA at 9th week after infection, compared to all the vaccinated groups of animals (G1, 2, 3 and 4)." (PMID 21765963, 2011). "Following infection with 200 Trichuris eggs (high dose), wild-type C57BL/6 (WT) mice develop a polarized CD4+ Th2 cell response characterized by high levels of IL-4, IL-5 and IL-13." (PMID 21573179, 2011). "We show that infection in AAD significantly reduced eosinophilic inflammation, OVA-induced IL-5, IL-13 and IFN-γ responses and AHR; however, infection increased airway neutrophil influx in response to OVA challenge." (PMID 21998577, 2011). "We analyzed the levels of IL-2, IL-4, IL-5, IL-10, IL-12(p70), GM-CSF, IFN-γ and TNF-α in the culture supernatant of macrophages 24 h post infection." (PMID 19680450, 2009). "Infection levels by Schistosoma are controlled by a major locus on chromosome 5q31-q33 containing the IL4, IL5 and IL13 genes related to the Th2 immune response." (PMID 19471606, 2008). "When infected guinea-pigs were treated with mAb anti-IL-5 (TRFK-5) given at the same time or 1 or 3 days after infection, there was a high percentage of reduction of eosinophil counts 18 days after infection." (PMID 18475693, 1996). "In wheezing children with MP infection, IL-5 concentrations were significantly higher in subjects with acute MPP infection than in those without such infection." (PMID 41313182, 2026).
infection (continued). "Upon challenge infection, elevated IgG- and IgA-secreting plasma cells, germinal center B cells, and memory B cells were observed, and CD4+, CD8+ T-cells, as well as both Th1 (IFN-γ) and Th2 (IL-4, IL-5) cytokines, were also increased." (PMID 41599200, 2026). "However, as the infection duration prolongs, IFN-γ, IL-2, and TNF-β significantly decrease (p < 0.05), while IL-5 significantly increases (p < 0.05), indicating that Th2-type humoral immunity becomes the main anti-parasitic mechanism." (PMID 40979361, 2025). "IL‐4, IL‐5, and IP‐10 in all individuals with COVID versus those without infection, regardless of DM status." (PMID 40476695, 2025). "Since IL-4 and IL-5 have previously been reported to promote mucus secretion in asthmatic patients, we examined their expression levels in the lung tissues of WT and LincR-PPP2R5C KO mice at 21 days post infection." (PMID 39287443, 2024). "The R2 of 0.683 suggests that levels of IL-5 and IL-3 and an environmental variable (i.e., the distance from the water source to the toilet) explained 68.3% of stunted children with STH infection; the remaining 31.7% were influenced by other factors that were not considered." (PMID 38393122, 2024). "In contrast with IL-4, IL-5, and IL-13, mRNA expression of IL-1β and TNF-α, both considered type 1 cytokines, decreased after infection with RV2, suggesting that RV infection on day 6 of life skewed the response to subsequent heterologous RV infection toward a type 2 phenotype." (PMID 38061015, 2024). "of ruminants can provoke serious health problems and because the infected host may modulate the infection through the activity of IL4, IL5, IL13, and the FCεR1A receptor genes." (PMID 39057830, 2024). "There was a significant (not for il-5 in the LB group) increase in the expression of il-5 and il-13 in all three infection groups compared to uninfected mice, with the PR group reaching the highest levels." (PMID 39466851, 2024). "Conversely, SmLE infection resulted in elevated levels of IL-2, IL-4, IL-5 and IL-6 and a decrease in IL-13 in C57BL/6 but not in BALB/c mice." (PMID 38711063, 2024). "IL-5, IL-13, and 25(OH)D levels were negative predictors of infection in stunted children, meaning that a child with lower IL-5, IL-13, and 25(OH)D levels would be more vulnerable to becoming ill if infected by STHs." (PMID 38393122, 2024). "Our results are in line with results reported in a previous rat model study, where no IL-4 or IL-5 was found in the vaginal fluid after inoculation, while a notable Th1 cytokine pattern was found during the primary infection." (PMID 37529322, 2023). "Despite a significant influx of Th2-dominant eosinophils to the airways of WT mice, IL-5 expression did not change during infection." (PMID 37795093, 2023). "At week 4 post infection, CD4+ T-cells showed a mixed response to S. mansoni AWA by secreting cytokines which encompassed Th1 (IFNγ, TNFα, IL-2 & IL-1β), Th2 (IL-4, IL-5, IL-13) and regulatory responses (IL-10) as well as the regulatory T cell transcription factor Foxp3." (PMID 37837930, 2023). "In contrast, we observed minimal expression of IL-5 by T cells in the lung in both naive mice and during infection, indicating that the major source of IL-5 is ILC2 derived rather than adaptive cells at this time point." (PMID 36602520, 2023). "Moreover, comparing the effect of the infection with the two filariod species on cytokine levels, it was found that INF-gamma and IL-5 levels were significantly higher in equines infected with S. digitata than those infected with Mansonella (T) sp." (PMID 36145411, 2022). "In contrast, mice lacking IL-5 showed reduced eosinophil counts at the site of infection as well as a higher adult worm and MF burden." (PMID 36389745, 2022).